FXYD2 (FXYD domain containing ion transport regulator 2)
Diseases named in the same sentence as FXYD2 in open-access papers (continued):
Sharing a sentence is not in itself a finding about the gene and the disease.
tumor (10 papers, 2016 to 2025). "The FXYD2 gene, which modulates Na+/K+-ATPase activity, is downregulated in ccRCC and is associated with tumor progression, unfavorable prognosis, and increased regulatory T cells (Tregs) infiltration." (PMID 40723891, 2025). "It has been reported that the high expression of FXYD2 gene is related to poor overall survival, which may cause changes in tumor microenvironment (TME) and lead to malignant tumors." (PMID 35651949, 2022). "Within these networks, we found that these four TFs regulated multiple tumor-specific genes, such as FXYD2 and CRYAB, with a significant increase in expression in tumor cells." (PMID 35853872, 2022). "With the help of the ESTIMATE algorithm, FXYD2 was revealed to conversely correlate with immune and stromal scores and positively related to tumor purity which was determined by the percentage of infiltrating immune or stromal cells." (PMID 36313180, 2022). "The protein expression levels of MGST1, MGST3, ABCG2, and FXYD2 differed among the G1-G4 DDP-resistant tumor tissues." (PMID 32158694, 2020). "Suppression of FXYD2 was shown to lead to a significant decrease in tumor growth rate, as well as tumor size in vivo." (PMID 26910837, 2016). "Together, our results suggest that the suppression of FXYD2 inhibits tumor formation by increasing autophagy activity." (PMID 26910837, 2016). "Decreased expression of FXYD2 could independently predict worse survival and correlate with advanced tumor grade and pathologic T stage." (PMID 36313180, 2022). "As the result demonstrated, FXYD2 expression, age, smoking, pharmaceutical intervention, tumor grade, pathologic stage, stage T, and stage M could predict the overall survival of ccRCC patients." (PMID 36313180, 2022). "We identified several markers specifically expressed in the C0 cluster that was tumor-infiltrated, such as checkpoint inhibitor (LAG3), cytotoxicity-associated genes (GZMK), and oncogenic driver gene (FXYD2), further indicating that these CD8+ T cells were exhausted." (PMID 35812372, 2022). "However, only FXYD2 expression, age, pharmaceutical intervention, tumor grade, and pathologic stage could independently predict the prognosis of ccRCC." (PMID 36313180, 2022). "A comparative analysis revealed that five sodium ion transport-related genes—FXYD2, ANK3, ATP1A1, PRSS8, and CHP1—were significantly downregulated in malignant cells, implicating their potential involvement in tumor suppression." (PMID 40723891, 2025). "Western blotting analysis revealed that six proteins (MGST1, MGST3, ABCG2, FXYD2, ALDH3A1, and GST-ω1) were differentially expressed among G1-G4 DDP-resistant tumor tissues." (PMID 32158694, 2020). "Silencing of FXYD2 expression in OCCC cells inhibited Na+/K+-ATPase enzyme activity and suppressed tumor growth via induction of autophagy-mediated cell death." (PMID 26910837, 2016). "Additionally, eight genes (ABCG2, ALDH3A1, FXYD2, GST-π1, GST-ω1, HMGCR, MGST1, and MGST3) were upregulated among the G1-G4 DDP-resistant tumor tissues." (PMID 32158694, 2020). "Thus, decreased urinary levels of FXYD2 and UMOD derived peptides may indicate inhibition of HNF1B transcriptional activity by a mediator released at the tumor site into the circulation." (PMID 31900160, 2020). "As for T cell exhaustion, notable negative relationship between FXYD2 expression and CTLA-4, TIGIT, and BTLA persisted before and after tumor purity adjustment." (PMID 36313180, 2022).
cancer (6 papers, 2016 to 2025). A tumor composed of atypical neoplastic, often pleomorphic cells that invade other tissues. "Changes in FXYD2 expression and genetic variants in FXYD2 were shown to be associated with an increased cancer risk in several studies." (PMID 39769162, 2024). "Other studies have shown that FXYD2 is already expressed in several types of cancer, and its expression is altered in many of them." (PMID 39769162, 2024). "In this specific type of cancer, FXYD2 levels can increase approximately 38-fold if we compare microarray data from clear cell cancer with those from ovarian and endometrial control cells." (PMID 39769162, 2024). "The mechanisms by which FXYD2 promotes cancer development are not fully understood." (PMID 39769162, 2024). "The current literature suggests that FXYD2 may play a role in cancer development and progression by regulating ion transport and signaling pathways involved in cell proliferation and survival." (PMID 39769162, 2024). "However, some studies have shown that FXYD2 is a promising tumor marker for specific types of cancer, such as clear cell ovarian cancer (OCCC), which has a very poor prognosis." (PMID 39769162, 2024). "As a member of this family, FXYD2 takes part in dealing with cancer." (PMID 36313180, 2022). "Upregulation of FXYD2 in cancer cells has been shown to confer dependence on FXYD2 for survival, and the inhibition of Na+/K+-ATPase by cardiac glycosides has a great therapeutic efficacy in OCCC cells expressing high levels of FXYD2 through an autophagic effect." (PMID 26910837, 2016). "FXYD2 can mediate cancer cell growth by regulating the activity of Na+/K+-ATPase." (PMID 26910837, 2016). "However, some studies have suggested that FXYD2 may contribute to cancer progression by regulating signaling pathways involved in cell proliferation and survival." (PMID 39769162, 2024). "For example, a study reported that FXYD2 promoted the activation of the PI3K/AKT signaling pathway, which is known to be involved in the survival and proliferation of cancer cells." (PMID 39769162, 2024). "Interestingly, we found that FXYD2 expression was positively correlated with the expression of a transcription factor, hepatocyte nuclear factor 1 homeobox B (HNF1B), in OCCC clinical specimens and cancer cell lines." (PMID 26910837, 2016).
infection (1 paper, 2016). The state of being infected such as from the introduction of a foreign agent such as serum, vaccine, antigenic substance or organism. "The differential gene expression observed at day 15 post-infection demonstrated a consistent pattern of gene up regulation of PHGDH and PSAT1 and down regulation of APOC1, FADS2, FXYD2, KIAA0125, and MMP12 over a period of time in HIV-1 infected PBMC." (PMID 26821323, 2016).
kidney disease (1 paper, 2019). "Physiological relevance with regard to kidney disease as indicated by literature research was found for two proteins (PYCR1, FXYD2)." (PMID 31083566, 2019).
metabolic disease (1 paper, 2025). A congenital disorder (due to inherited enzyme abnormality) or acquired (due to failure of a metabolically important organ) disorder resulting from an abnormal metabolic process. "Therefore, the proposed patho-mechanism of FXYD2-related metabolic disease needs to be verified in other patients with similar biochemical defects." (PMID 40428357, 2025).
FXYD2 also shares sentences with these, for which no sentence is quoted: breast carcinoma (2 papers); prostate carcinoma (2); Alcoholism (1); Anxiety (1); Bartter syndrome type 3 (1); Bartter syndrome type 4 (1); bladder cancer (1); Dupuytren’s Disease (1); Gitelman syndrome (1); hypokalemic alkalosis (1); invasive breast carcinoma (1); liver cancer (1); lung squamous cell carcinoma (1); oligodendroglioma (1); osteosarcoma (1); polycystic kidney disease (1); renal hypomagnesemia 2 (1); Stroke (1); thyroid cancer (1).